TIGD6 (tigger transposable element derived 6)
Synonyms: DKFZp761E2110
Tractability: PROTAC: ubiquitination databases record sites on it.
Gene: Protein-coding gene on chromosome 5 (149,993,118 to 150,000,654, reverse strand). Ensembl gene ENSG00000164296.
Subcellular location: Nucleus
Subcellular location (Human Protein Atlas): Nucleoplasm; Actin filaments; Vesicles
Gene Ontology:
Molecular function: DNA binding; nucleic acid binding
Cellular component: nucleus
Genetic constraint (gnomAD): Loss-of-function variants: 9 observed, 11.47 expected, observed/expected ratio (o/e) 0.78, 90% interval 0.47 to 1.37. The upper end of that interval is the gene's LOEUF score, 1.37, which puts it in group 5 of 6, group 1 being the genes least tolerant of losing a copy. Missense variants: 584 observed, 647.03 expected, observed/expected ratio (o/e) 0.9, 90% interval 0.84 to 0.97. Synonymous variants: 186 observed, 228.1 expected, observed/expected ratio (o/e) 0.82, 90% interval 0.72 to 0.92.
Homologues: Orthologues: chimpanzee TIGD6 (99% identical), macaque TIGD6 (97% identical), tropical clawed frog tigd3 (21% identical), tropical clawed frog XB5896327 (4% identical). Paralogues in human: TIGD4 (28% identical), CENPB (25% identical), TIGD1 (25% identical), TIGD7 (25% identical), JRKL (23% identical), TIGD5 (23% identical), TIGD2 (22% identical), TIGD3 (20% identical), JRK (19% identical), POGK (16% identical), POGZ (14% identical).
Diseases named in the same sentence as TIGD6 in open-access papers:
TIGD6 is named in the same sentence as 2 diseases in open-access papers, as found by Europe PMC text mining. Sharing a sentence is not in itself a finding about the gene and the disease. The quoted sentences say what the papers report.
cancer (1 paper, 2021). A tumor composed of atypical neoplastic, often pleomorphic cells that invade other tissues. "The MAT2A node includes TIGD6, which has not been associated with cancer." (PMID 34797887, 2021).
TIGD6 also shares sentences with these, for which no sentence is quoted: tumour (1 paper).